MIR670 (microRNA 670)
Synonyms: hsa-mir-670
Gene: MicroRNA gene on chromosome 11 (43,559,656 to 43,559,753, forward strand). Ensembl gene ENSG00000211568.
Homologues: Orthologues: macaque mml-mir-670 (100% identical).